LINC00290 (long independently transcribed non-coding RNA 290)
Synonyms: NCRNA00290
Gene: Long non-coding RNA gene on chromosome 4 (181,036,398 to 181,159,473, reverse strand). Ensembl gene ENSG00000248197.
Diseases named in the same sentence as LINC00290 in open-access papers:
LINC00290 is named in the same sentence as 3 diseases in open-access papers, as found by Europe PMC text mining. Sharing a sentence is not in itself a finding about the gene and the disease. The quoted sentences say what the papers report.
cervical cancer (1 paper, 2022). A primary or metastatic malignant neoplasm involving the cervix. "Combined with the corresponding RNA-seq data, we highlight LINC00290, LINC02500 and LENG9 as potential driver genes in cervical cancer." (PMID 35538075, 2022). "We further highlighted LINC00290, LINC02500, and LENG9 as potential driver genes in cervical cancer." (PMID 35538075, 2022). "Combined with the corresponding RNA-seq data, we highlighted LINC00290, LINC02500, and LENG9 as potential driver genes in cervical cancer." (PMID 35538075, 2022). "Combining this with the corresponding RNA-seq data, we were able to pinpoint LINC00290, LINC02500, and LENG9 as potential driver genes in cervical cancer." (PMID 35538075, 2022).
cancer (2 papers, 2019 to 2022). A tumor composed of atypical neoplastic, often pleomorphic cells that invade other tissues. "Using DNA copy number data from 9,744 human cancer specimens, we demonstrate that linear deletion limitation exists and exposes deletion-limiting genes for seven known deletion targets (CDKN2A, RB1, PTEN, MAP2K4, NF1, SMAD4, and LINC00290)." (PMID 31341961, 2019). "Using DNA copy number copy number data from 9744 cancer specimens belonging to 39 cancer subtypes, we show that linear deletion limitation exists, and exploit it to expose deletion-limiting genes for seven deletion targets (CDKN2A, RB1, PTEN, MAP2K4, NF1, SMAD4, and LINC00290)." (PMID 31341961, 2019).
tumor (1 paper, 2022). "However, our current large-range high-resolution results suggest the recently annotated LINC02500 may be a tumor suppressor candidate gene, while LINC00290 may be an oncogene candidate gene." (PMID 35538075, 2022).